CORO1B (coronin 1B)
Description:
Regulates leading edge dynamics and cell motility in fibroblasts. May be involved in cytokinesis and signal transduction (By similarity).
Synonyms: coronin-2
Tractability: Antibody: its Gene Ontology location is reachable by antibodies, with high confidence; the Human Protein Atlas places it where antibodies can reach. PROTAC: ubiquitination databases record sites on it; its protein half-life has been measured.
Gene: Protein-coding gene on chromosome 11 (67,435,510 to 67,443,821, reverse strand). Ensembl gene ENSG00000172725.
Subcellular location: Cytoplasm, cytoskeleton; Cytoplasm, cytoskeleton, stress fiber
Subcellular location (Human Protein Atlas): Cytosol; Plasma membrane
Gene Ontology:
Molecular function: actin filament binding; Arp2/3 complex binding; cadherin binding; identical protein binding; protein binding
Biological process: actin cytoskeleton organization; actin filament branching; actin filament bundle assembly; cell migration; cellular response to platelet-derived growth factor stimulus; endothelial cell chemotaxis; negative regulation of Arp2/3 complex-mediated actin nucleation; negative regulation of smooth muscle cell chemotaxis; positive regulation of lamellipodium morphogenesis; protein localization to cell leading edge; ruffle organization; wound healing; actin filament organization; regulation of Arp2/3 complex-mediated actin nucleation; negative regulation of cellular component organization
Cellular component: actin filament; cell leading edge; cell periphery; cytoplasm; cytosol; extracellular exosome; focal adhesion; lamellipodium; perinuclear region of cytoplasm; plasma membrane; stress fiber; cytoskeleton; glutamatergic synapse; synapse
Genetic constraint (gnomAD): Loss-of-function variants: 30 observed, 51.33 expected, observed/expected ratio (o/e) 0.58, 90% interval 0.44 to 0.79. The upper end of that interval is the gene's LOEUF score, 0.79, which puts it in group 3 of 6, group 1 being the genes least tolerant of losing a copy. Missense variants: 648 observed, 691.75 expected, observed/expected ratio (o/e) 0.94, 90% interval 0.88 to 1. Synonymous variants: 310 observed, 286.66 expected, observed/expected ratio (o/e) 1.08, 90% interval 0.99 to 1.19.
Homologues: Orthologues: chimpanzee CORO1B (99% identical), macaque CORO1B (98% identical), mouse Coro1b (94% identical), guinea pig CORO1B (93% identical), rat Coro1b (93% identical), pig CORO1B (87% identical), dog CORO1B (74% identical), zebrafish coro1b (62% identical), Drosophila melanogaster coro (53% identical), Caenorhabditis elegans cor-1 (47% identical). Paralogues in human: CORO1C (71% identical), CORO6 (66% identical), CORO1A (63% identical), CORO2A (44% identical), CORO2B (42% identical), CORO7 (33% identical).
Diseases named in the same sentence as CORO1B in open-access papers:
CORO1B is named in the same sentence as 13 diseases in open-access papers, as found by Europe PMC text mining. Sharing a sentence is not in itself a finding about the gene and the disease. The quoted sentences say what the papers report.
head and neck squamous cell carcinoma (1 paper, 2020). A squamous cell carcinoma that arises from any of the following anatomic sites: lip and oral cavity, nasal cavity, paranasal sinuses, pharynx, larynx, and salivary glands. "In head and neck squamous cell carcinoma cells, Coronin 1B, a coronin with significant homology to Coronin 1C, has been shown to regulate exosome secretion via destabilization of the actin network at MVB docking sites through interactions with cortactin and Rab27a71." (PMID 32686704, 2020).
ovarian carcinoma (1 paper, 2025). A malignant neoplasm originating from the surface ovarian epithelium. "Thereby, we revealed a signature of three TOP genes encoding proteins within our dataset (CORO1B, LAMP2, MSLN), which were differentially expressed in ovarian cancer patients compared to healthy individuals." (PMID 41551606, 2025).
pancreatic ductal adenocarcinoma (1 paper, 2023). An infiltrating adenocarcinoma that arises from the epithelial cells of the pancreas. "Analysis of large cohort data from The Cancer Genome Atlas revealed that expression of CORO1A, CORO1B, CORO1C, CORO2A, and CORO7 was significantly upregulated in pancreatic ductal adenocarcinoma (PDAC) tissues (p < 0.05)." (PMID 37239355, 2023).
prostate carcinoma (1 paper, 2019). A carcinoma that arises from epithelial cells of the prostate gland. "Maybe most interestingly in regard to our data on promotion of prostate cancer cell motility by PIM1 and NFATC1, there were several genes encoding regulators of the cytoskeletal actin network (INF2, FHOD1, ACTN3, CORO1B) and cell adhesion (COL6A2, PXN, ITGA5)." (PMID 31730483, 2019).
tumor (4 papers, 2012 to 2025). "The results showed that the expression levels of CORO1B, GOLGA7, PCSK4, ST6GALNAC4, and ZSWIM1 in normal tissues were significantly higher than those in tumor tissues, which were similar to the trends detected in the TCGA dataset." (PMID 34970268, 2021). "Taken together, our single-cell RNA expression analysis affirmed that SELPLG and SH2D2A are differentially regulated in single tumor-infiltrating L1CAM-CAR T cells, suggesting a functional role, while TIAM2, CORO1B and MYH10 do not seem to influence L1CAM-CAR T cell migration." (PMID 41394860, 2025).
infection (1 paper, 2021). The state of being infected such as from the introduction of a foreign agent such as serum, vaccine, antigenic substance or organism. "For instance, the proteins FMNL3, EPB41L1, SSH2, CORO1B and ARPC2 are detected only in E. ruminantium-infected cells, while in FSCN1 and GC, proteins are under-expressed or inhibited by infection." (PMID 34073568, 2021).
vasculopathies (1 paper, 2021). "Coronin 1B (Coro1B) is one of the actin binding proteins that can regulate platelet-derived growth factor (PDGF)-induced vascular smooth muscle cell (VSMC) migration, suggesting a new therapeutic target for vasculopathies." (PMID 34970268, 2021).
CORO1B also shares sentences with these, for which no sentence is quoted: breast carcinoma (1 paper); cancer (1); chronic gastritis (1); cognitive decline (1); gastric cancer (1); metastatic cancer (1).